MALAT1 (metastasis associated lung adenocarcinoma transcript 1)
Diseases named in the same sentence as MALAT1 in open-access papers (continued):
Sharing a sentence is not in itself a finding about the gene and the disease.
tumor (continued). "KMD3A, another H3K9 demethylating enzyme, was found to induce MALAT1 expression in MM cells that contributed to the establishment of hypoxic niches supporting tumor growth." (PMID 29739426, 2018). "MALAT1 induces autophagy in tumor cells under hypoxia and stabilizes HIF-1a in human liver L-02 cells." (PMID 29435112, 2018). "We first measured the expression level of MALAT1 in the collected 42 OS tissue specimens and paired para‐tumor tissue specimens by qRT‐PCR." (PMID 30094957, 2018). "Metastasis-associated lung adenocarcinoma transcript 1 (MALAT1) is an 8000 nt lncRNA, upregulated in many different human tumours." (PMID 30037059, 2018). "The binding specificity of 5’ (Cy5.5)-MALAT1 ASO to tumour cells was determined using fluorescence activated cell sorter (FACS) studies." (PMID 29156758, 2017). "Thirdly, a further correlation analysis confirmed that the high level of MALAT1 was closely correlated with clinicopathological features, especially with regard to clinical stage, distant metastasis and tumor size (determined by using qRT-PCR)." (PMID 28938647, 2017). "Another lncRNA, MALAT1, regulates complex biological processes, such as synaptogenesis, the invasion of trophoblasts into the uterine wall and tumor metastasis, by interacting with the serine/arginine-rich splicing factors." (PMID 29299179, 2017). "in vivo optical imaging exhibited 5’ (Cy5.5)-MALAT1 ASO uptake in the tumour with a maximum at 30 min p.i. that slowly washed out over time." (PMID 29156758, 2017). "In our sample set 1 MALAT1 expression was diminished in invasive tumours compared to benign tissues, whereas NMIBC displayed rather upregulation." (PMID 28430799, 2017). "Next, we tried to elucidate how MALAT1 acts in gastric carcinogenesis through validation of some of its targets that are tumor suppressor genes." (PMID 28077118, 2017). "The lncRNA MALAT1 has been observed and considered as a pro-oncogene in an expanding list of human tumor tissues or cell lines." (PMID 27966454, 2017). "To create the probe, we selected the Cy5.5 dye, which is used as a promising contrast agent for the in vivo demarcation of tumours, to conjugate with the MALAT1 ASO." (PMID 29156758, 2017). "The 5’ (Cy5.5)-MALAT1 ASO uptake in the tumour showed a maximum at 30 min p.i. and slowly washed out over time." (PMID 29156758, 2017). "5’ (Cy5.5)-MALAT1 ASO exhibited high contrast tumour-to tissue ratios for the imaging of dissected tissues and organs, which were consistent with the in vivo imaging findings." (PMID 29156758, 2017). "In conclusion, the main finding of this study was that MALAT1 acts as a tumour promoter at least in part by binding miR-217 and sequestering the molecule in the nucleus, thereby promoting oncogenic KRAS expression in PDAC." (PMID 28701723, 2017). "The in vitro cell and in vivo animal studies had revealed that the expression level of lncRNA MALAT1 is related to cell migration potential and tumor growth." (PMID 28253859, 2017). "For example, knockdown of long non-coding RNA MALAT1 increases the blood-tumor barrier permeability by up-regulating miR-140." (PMID 28396617, 2017). "Over-expression of MALAT1 indicates a more aggressive feature of the tumor and predicts a poorer OS than down-expression of MALAT1 in patients with ccRCC." (PMID 28467794, 2017). "Consistent with in vitro observations, we observed that while chemotherapeutics greatly decreased tumor volume, MALAT1 overexpression significantly increased the chemoresistance." (PMID 29162158, 2017). "Unexpectedly, in view of previous reports on MALAT1 overexpression in UC, MALAT1 expression was rather diminished in UC cell lines and tumour tissues compared to normal tissues in our cohorts." (PMID 28430799, 2017). "We found that the expression of MALAT1 was higher in HCC tissues than that in tumor-adjacent tissues (P<0.01)." (PMID 28404923, 2017).
tumor (continued). "MALAT1 knockdown in NPC sensitizes the tumor cells to ionizing radiation and reduces the percentage of ALDH1-postive cells displaying properties associated with CSCs." (PMID 27802187, 2017). "Such as, previous studies suggested that long non-coding RNA MALAT1 promoted tumor growth and metastasis by inducing epithelial-mesenchymal transition in oral squamous cell carcinoma." (PMID 28396617, 2017). "Deep invasion of tumor (advanced T stages) was more common in the high MALAT1-level group (p = 0.039)." (PMID 28077118, 2017). "5’ (Cy5.5)-MALAT1 ASO uptake in the tumour was maximum at 30 min p.i. and slowly washed out over time." (PMID 29156758, 2017). "Meanwhile, the expression of MALAT1 was negatively related to tumor size (OR=1.29, 95% CI: 1.05-1.59)." (PMID 29113381, 2017). "In vitro and vivo experiments, MALAT1 exhibits a pro-tumor function in the proliferation, invasion and migration of CCA cells." (PMID 29246025, 2017). "In gallbladder, high expression level of MALAT1 is correlated with larger tumor size, lymphatic metastasis and shorter overall survival; silencing of MALAT1 inhibits cell proliferation, cell invasion and increases cell apoptosis." (PMID 28881680, 2017). "Tumor volume in the MALAT1 overexpression (MALAT1++) group was visibly greater than that found in the negative control (MALAT1-) group at the 4th day after inoculation." (PMID 28938647, 2017). "Silencing MALAT1 significantly up-regulated the expression of miR-183, conversely, over-expression of MALAT1 inverted the inhibitory effect of miR-183 on the tumor growth in vitro and in vivo." (PMID 27966454, 2017). "The present study identified a near-infrared molecular imaging probe for cells over-expressing MALAT1 that allows for non-invasive specific detection of tumours in vitro and in vivo." (PMID 29156758, 2017). "The results of the forest plot suggested that tumor weight was significantly decreased by down-regulating tumor onco-lncRNA MALAT1 expression." (PMID 29245999, 2017). "In vitro and in vivo experiments, MALAT1 indicates a pro-tumor function in the proliferation, invasion, and migration of cholangiocarcinoma cells." (PMID 29299179, 2017). "Our proposed Cy5.5 labelling of MALAT1 ASO can serve as a potent optical probe for in vivo imaging of tumour expressing MALAT1." (PMID 29156758, 2017). "MALAT-1 also increases ratio of pancreatic CSCs and multidrug resistance, maintains self-renewing capacity, and accelerates tumor angiogenesis." (PMID 29110645, 2017). "It has been reported that MALAT1 overexpression enhances cell proliferation and migration in vitro, and promotes tumor growth and metastasis in nude mice, due to tumor suppressor gene SFPQ and proto-oncogene PTBP2." (PMID 27888635, 2017). "The 5’ (Cy5.5)-MALAT1 ASO was predominantly taken up by the MHCC-LM3 tumour at 24 h p.i, as seen in the imaging results in vivo." (PMID 29156758, 2017). "This study reports the method for preparing molecular optical imaging probes (antisense probes with a Cy5.5 emitter on its 5′equivalent end) for specific targeting of overexpressing MALAT1 tumours cells." (PMID 29156758, 2017). "For example, lncRNA metastasis-associated lung adenocarcinoma transcript 1 (MALAT1) was highly expressed in OS tissues and cells and promoted OS cell growth and tumor progression by inhibiting miR-376a." (PMID 28720111, 2017). "It is noteworthy that majority (9/13) of the MALAT1 underexpressed tumours was of triple-negative (HR−/ERBB2−) subtype." (PMID 27172249, 2016). "The high Malat1 levels correlated positively with tumor size and lymphatic metastasis, and correlated negatively with overall survival." (PMID 27191262, 2016). "The expression of MALAT1 in 38 paired samples (OS specimens and corresponding adjacent non-tumor tissues) was examined by real-time qPCR." (PMID 27458156, 2016).
tumor (continued). "Next, we attempted to identify the downstream target genes of MALAT1, the altered expression of which in MALAT1-expression altered cells, contributes to changes in cell proliferation, tumor progression and metastasis." (PMID 27250026, 2016). "MALAT1-overexpressed tumour epithelial cells showed marked diffuse nuclear signals and numerous huge nuclear speckles." (PMID 27172249, 2016). "In order to explore the potential role of circulating cell-free lncRNAs as the biomarkers for the diagnosis of BC, we first analyzed the correlation of MEG3, SNHG16 and MALAT1 expression levels between 36 serum samples and corresponding tumor tissue samples." (PMID 27793008, 2016). "We detected specific MALAT1 RNA in epithelial and stromal cells of all ten tumour samples studied by in situ hybridisation (ISH)." (PMID 27172249, 2016). "On the basis of our findings, we propose a model in which RBM24 plays a role as a tumor suppressor through the upregulation of miR-25, which directly targets MALAT1 for degradation." (PMID 27584791, 2016). "As compared with normal breast tissues, 24 (5.4%) tumours showed Δsv-MALAT1 mRNA overexpression (NΔsv-MALAT1 from 3.16 to 8.4), and surprisingly 84 (18.8%) tumours showed Δsv-MALAT1 mRNA underexpression (NΔsv-MALAT1 from 0.05 to 0.32)." (PMID 27172249, 2016). "On the other hand, when both HULC and MALAT1 were overexpressed, the average xenograft tumor weight increased to approximately 3.5 folds of the control weight (2.23 grams versus 0.68, t-test, P < 0.01)." (PMID 27782152, 2016). "Based on the data obtained from BC cell lines and BC patients, MALAT1 facilitates tumor progression differently in various BC subtypes." (PMID 27250026, 2016). "Specially, MALAT1 expression was found to be significantly higher at later stages of tumor development and in tumors that had undergone extensive metastasis." (PMID 27486823, 2016). "Metastasis Associated Lung Adenocarcinoma Transcript 1 (MALAT1) is one of the best-characterized lncRNAs with multiple functions, including triggering EMT in tumor cells and promoting tumor metastasis." (PMID 27019196, 2016). "In vivo, tumour volumes were significantly decreased in the MALAT1 silencing group compared with those in the control group." (PMID 27420766, 2016). "Upregulation of Malat1 correlated positively with tumor size (P = 0.013) and lymphatic metastasis (P = 0.005) while correlating negatively with overall survival (OS)." (PMID 27191262, 2016). "In general, Myc-6 appears to exert its tumor-suppressive effects, at least in part, through the specific downregulation of MALAT1." (PMID 27685633, 2016). "Nucleus of the MALAT1-overexpressed tumour epithelial cells showed marked diffuse nuclear signals and numerous huge nuclear speckles." (PMID 27172249, 2016). "High Malat1 levels correlate positively with tumor volume and lymphatic metastasis while correlating negatively with overall survival (OS)." (PMID 27191262, 2016). "lncRNAs involved in the regulation of tumor metastasis have also been reported, and include MALAT-1 and HOX antisense intergenic RNA (HOTAIR)." (PMID 27154193, 2016). "Tumours formed by MALAT1‐silenced cells grew much slower than those formed by control cells, and the tumour volumes from the MALAT1 knockdown group were significantly smaller than those from the control group." (PMID 27420766, 2016). "On the other hand, Pten plus the large non-coding RNAs Malat1 and Neat1 were among the 80 down-regulated genes with mRNA processing, nuclear bodies, ER-stress response and tumor suppression as relevant terms." (PMID 27801298, 2016). "In castrated male nude mice, siRNA-mediated silencing of MALAT1 delayed tumor growth and inhibited PCa cell metastasis." (PMID 27686732, 2016). "Our results thus support the potential use of monitoring MALAT1 expression level as a predictor of tumor recurrence and metastasis in patients diagnosed with ER negative lymph node negative BC." (PMID 27250026, 2016).
tumor (continued). "Higher MALAT1 expression was detected both in clear cell renal cell carcinoma (ccRCC) tissues than in adjacent non-tumor tissues and also in kidney cancer cells than normal epithelial HK-2 cells." (PMID 27686732, 2016). "Knockdown of MALAT-1 expression suppressed tumor cell proliferation, migration, and invasion, arrested cells at the G0/G1 phase of cell cycle, and induced apoptosis." (PMID 27227769, 2016). "This is consistent with documented evidence that transient MALAT1 overexpression enhanced tumor proliferation in cell lines and xenograft tumor formation in nude mice, while its attenuation resulted in reduced tumorigenicity." (PMID 26917489, 2016). "Systemic knockdown of MALAT1 through subcutaneous injection of ASOs inhibits tumor proliferation and metastasis, and induces differentiation." (PMID 27998273, 2016). "Our observations are in agreement with the recent data, showing the involvement of MALAT1 in tumor progression in luminal cells." (PMID 27250026, 2016). "When MALAT1 was overexpressed, the xenograft tumor weight increased approximately two folds when compared to the corresponding control group (1.48 grams versus 0.68 grams, t-test, P < 0.01)." (PMID 27782152, 2016). "MALAT1 expression level, tumor size, lymph node status, and lymphovascular invasion (LVI) status were included in a multivariate Cox regression analysis." (PMID 27191888, 2016). "Our data demonstrates a significant overexpression of MALAT1 in tumor samples compared to healthy controls." (PMID 26895470, 2016). "Higher MALAT1 expression is correlated with higher Gleason score, higher tumor stage and castration-resistant PCa." (PMID 27014907, 2016). "It possibly exerts its tumor suppressor function via increasing the expression of miR-25, which directly targets MALAT1 for degradation." (PMID 27584791, 2016). "MALAT1-overexpressed tumour epithelial cells showed marked diffuse nuclear signals and numerous nuclear speckles of variable size and shape as compared with MALAT1 normal-expressed tumour epithelial cells." (PMID 27172249, 2016). "HULC and/or MALAT1 overexpression resulted in early xenograft tumor formation compared to the control group (7.2days, 7.5days, 5.8 days versus 10.8days, respectively t-test, P < 0.01)." (PMID 27782152, 2016). "For example, MALAT1-depleted human cells showed changes in the alternative splicing of pre-mRNAs of several genes that are involved in tumor progression and metastasis." (PMID 27250026, 2016). "This has already been demonstrated in lung cancer, where antisense oligonucleotide blocking of MALAT1 prevented the spread of metastasis after tumour implantation in a mouse xenograft." (PMID 27092491, 2016). "We observed that TNBC cells that were either overexpressing or depleted of MALAT1 showed altered expression of genes that are involved in cell cycle, tumor progression and EMT." (PMID 27250026, 2016). "We also investigated the effect of tumor stemness genes after cells transfected with si-MALAT1 by qRT-PCR, we found that silencing MALAT1 down-regulated the expression of OCT4 and Nanog genes (P=0.0022, P=0.0005)." (PMID 27015363, 2016). "After injection of MALAT1 knock-out cells in the nude mice, the number of tumor nodules was reduced." (PMID 27143813, 2016). "In this regard, in contrast to the FL-MALAT1 expression, survival analysis revealed that patients with low-Δsv-MALAT1-expressed tumours had shorter MFS." (PMID 27172249, 2016). "To evaluate the effects of MALAT1 deletion on tumor cell proliferation, we used MTT and colony formation assays." (PMID 27998273, 2016). "We also observed faster tumor growth in the miR-124 inhibitor group compared with the control group and the miR-124 inhibitor+MALAT1-siRNA inversed the effect of the miR-124 inhibitor on tumor growth in vivo." (PMID 26918449, 2016).
tumor (continued). "We found that the MALAT1 expression level was gradually increased in ESCC patients in line with WHO stage (P=0.0395, P=0.0331) and revealed that MALAT1 was predominantly up-regulated in late-stage tumor tissues." (PMID 27015363, 2016). "During the entire tumor growth period, we observed slower tumor growth in the MALAT1-siRNA group compared with the control group." (PMID 26918449, 2016). "The ccRCC patients with higher MALAT1 level more often had advanced clinical features (such as greater tumor size, depth of tumor invasion, and lymphatic invasion) and poor survival rate." (PMID 27686732, 2016). "Targeted deletion of Malat1 in human lung tumor cells impairs tumor metastasis in a mouse xenograft model." (PMID 26335021, 2015). "The tumor weight and tumor growth curve suggested that, MALAT1 inhibition suppressed effectively tumor growth comparing with the control and scramble treated xenograft tumors (P < 0.05)." (PMID 26522444, 2015). "Up to 42 days, there was a dramatic decrease in tumor volume and weight in the sh-MALAT1 group compared with sh-LacZ group." (PMID 26461224, 2015). "Inhibition of MALAT1 suppressed tumor proliferation in vitro and in vivo, as well as the migratory and invasive capacity." (PMID 25613496, 2015). "The results showed that MALAT-1 knockdown reduced the formation of spheres significantly, and the size of tumor spheres in M-si1 groups was significantly smaller than that of M-nc groups." (PMID 25811929, 2015). "For a more detailed analysis, conditional Malat1 knockout models would be needed to delete this lncRNA at a certain stage during the tumor development, or in a specific compartment of the tumor environment (endothelial cells vs. epithelial tumor cells)." (PMID 25580533, 2015). "We next detected the copy number of MALAT1 in the 54 tumor tissues by AccuCopyTM, for MALAT1 is located on human chromosome 11q13, which is reported to be frequently amplified in ESCC tissues." (PMID 25613496, 2015). "The methylation status of the CpG island in the MALAT1 promoter was explored by bisulfite sequencing, while the copy numbers in tumor tissues and blood samples were detected by a well-established AccuCopyTM method." (PMID 25613496, 2015). "We validated that MALAT1 was overexpressed in OSCC tumor samples compared with the normal oral mucosa samples, and MALAT1 over-expression confers a shorter survival." (PMID 26522444, 2015). "Inhibition of MALAT1 suppressed tumor growth in vitro and in vivo, as well as cell migratory and invasive capacity, confirming its oncogenic roles in ESCC." (PMID 25613496, 2015). "A number of studies provided evidence that ectopic expression of MALAT1 promotes proliferation and migration of cell lines in vitro and enhances tumor growth and metastasis in vivo." (PMID 26064090, 2015). "The inhibitory effect of MALAT1 knockdown on ESCC proliferation was also observed in a nude mice tumor growth model." (PMID 25613496, 2015). "We then detected the expression of ZEB2, miR-200c and MALAT1 in 40 tumor specimens and their paired normal adjacent tissues by real-time PCR." (PMID 26461224, 2015). "MALAT1 significantly increased colony formation and migration of cells in soft agar colony formation and wound healing assays in vitro and it promoted tumor growth and lung metastasis in a mouse model in vivo." (PMID 26307974, 2015). "Results from ESCC tissues further supported the idea that MALAT1 promotes tumor growth by inactivating the cell cycle checkpoint." (PMID 25613496, 2015). "Some of lncRNAs, such as HOTAIR and MALAT-1, are proposed to promote tumor cell metastasis, but further functional tests are required." (PMID 26415221, 2015).